CD4 (CD4 molecule)
Diseases named in the same sentence as CD4 in open-access papers (continued):
Sharing a sentence is not in itself a finding about the gene and the disease.
Obesity (continued). "This association appears to be independent of age, HIV-clinical parameters (CD4 nadir and latest, CD4/CD8 ratio, HIV RNA zenith and latest, viral blips, HIV and ART duration, and HIV medication), and other recognized pro-inflammatory risk factors (obesity and smoking status)." (PMID 36157576, 2022). "Overall, DCs, B cells, macrophages and adipocytes have reported APC activity in AT as discussed superficially above and in more detail below, but there is no consensus on whether any of these APC subsets dominates CD4+ T cell activation and thus T cell inflammation in obesity-expanded AT." (PMID 31379820, 2019). "Although some have reported improved immune benefits of being overweight such as greater CD4 response after HAART initiation, others have found smaller increases in CD4 counts and percentages in obese compared with normal weight persons, suggesting that obesity might impair CD4 recovery." (PMID 26699870, 2015). "Here, ASCs were obtained from 2 groups, donors with T2D and obesity (dASCs) or nondiabetic donors with normal-weight (ndASCs), and then cultured with anti-CD3/CD28-stimulated allogeneic CD4 T cells." (PMID 36945068, 2023). "CD4+ T cell depletion markedly reduced the number of CD8+ T cells in the tumor, as well as the effect of obesity, with no such reduction being observed in the blood and spleen." (PMID 36611881, 2022). "The counts of CD4+ cells and CD8+ cells were also decreased in the obesity group, while the differences were not significant." (PMID 33746594, 2021). "The majority of active older adults participants, regardless of body mass, had a CD4/CD8 value within the reference range and only 14% of active adults with obesity had an inverted CD4/CD8." (PMID 33752623, 2021). "Glucose homeostasis typically becomes dysregulated in diet-induced obesity, when numbers of IFN-γ-secreting TH1 cells overwhelm the non-expending pools of TH2 (CD4+GATA-3+) and Tregs (CD4+CD25+Foxp3+)." (PMID 32581740, 2020). "Obesity did not alter the percentages of circulating IFNγ+ CD8 T cells or IFNγ+, IL-4+, or IL-17A+ CD4 T cells in ccRCC subjects." (PMID 32469992, 2020). "In this paper, we have characterized the phenotype and functional properties of VAT-derived CD4 conventional T cells (Tconv) and CD8 T cells in physiology (leanness condition) and in obesity with and without dysglycemia." (PMID 32299896, 2020). "There was marked inter-sample variability amongst subjects when expressed per gram of tissue; CD4+ T cells, when expressed as a percentage of total CD3+, showed a non-significant decreased with human obesity." (PMID 21298111, 2011). "We might have underestimated the prevalence of overweight or obesity because those who were not eligible to start ART could be in the early stage of HIV infection and have higher CD4 counts." (PMID 37900013, 2023). "The antigens presented by major histocompatibility complex (MHC) class II proteins may induce the expansion of CD4+ T cells and their differentiation into inflammatory effectors in VAT during obesity, although the nature of these antigens is not yet clear." (PMID 34572084, 2021). "Although reduced CD4 expression was not accompanied by fasting-induced alterations in T cell cytokine secretion, the differential T cell IFN-γ (higher in L-BMI) and IL-17 (higher in O-BMI) secretion in the basal state are indicative of altered T cell functionality in obesity." (PMID 40662191, 2025). "Notably, the multivariable analysis of HTN confirmed the strong independent predictive capacity of increased age, obesity, and dyslipidemia, while none of the studied HIV-specific parameters including CD4 cell count, viral load, or duration of the infection showed a significant association with HTN." (PMID 41302171, 2025). "Further studies of chemokine receptors on CD4+ and CD8+ T cells may provide insight into whether HIV infection results in signals that preferentially recruit CD8+ T cells over CD4+ T cells independent of obesity." (PMID 30941121, 2019).
Obesity (continued). "Activation of CD4+ memory cells that recognized non-pancreatic beta cell autoantigens, such as e.g., oxidized LDL or intestinal-derived products, by a proinflammatory cytokine environment generated during obesity or type 2 diabetes may also account for these relationships." (PMID 26458065, 2015).
atherosclerosis (359 papers, 2005 to 2026). A disease characterized by the build-up of fatty material and calcium deposition in the arterial wall resulting in partial or complete occlusion of the arterial lumen. "In conclusion, CD4+ nadir and this combined pattern were associated with greater cIMT severity, supporting a role for immune dysregulation in subclinical atherosclerosis." (PMID 41902291, 2026). "For example, CD4+ T cells are involved in inflammatory responses in atherosclerosis and hypertension, while CD8+ T cells are linked to tissue injury and repair mechanisms during myocardial infarction and stroke." (PMID 39940640, 2025). "Legumain deficiency impairs TCR signaling, CD4+ T cell survival and proliferation, and reduces the formation and function of effector T cells in Apoe−/− mice, conferring protection against atherosclerosis." (PMID 39473192, 2025). "RYR2 regulates T-cell calcium signaling, and gain-of-function mutations lead to increased IL-2 secretion in CD4+ T cells, which is a novel immune cell infiltration-related biomarker in atherosclerosis diagnosis." (PMID 40894479, 2025). "Recently, a higher value of pan CD4+T cells was found to be associated with lower endothelial function in participants of the Multi-Ethnic Study of Atherosclerosis." (PMID 40852715, 2025). "Next, we provided a more detailed analysis of the effector CD4+ T cell phenotype, as different T helper subsets have distinct roles in atherosclerosis progression, dependent on their hallmark cytokine secretion." (PMID 40603813, 2025). "This is supported by findings from the Multi-Ethnic Study of Atherosclerosis, which show that Naïve and memory CD4+ T cells are linked to type II diabetes and subclinical atherosclerosis in a cross-sectional manner." (PMID 39765677, 2024). "Arterial APCs present atherosclerosis-associated peptides to naïve CD4+ and CD8+ T cells in secondary lymphoid organs via major histocompatibility complex (MHC) molecules, alongside co-stimulatory signals and cytokines that drive T cell polarization." (PMID 39766344, 2024). "Studies have shown that different subgroups of CD4+ T cells are associated with atherosclerosis and coronary artery disease in the atherosclerosis process." (PMID 39610972, 2024). "The role of CD4+ T-cells and their associated cytokines in atherosclerosis or coronary artery disease in ART-treated PLWH remains poorly documented, with some recent studies documenting the expansion of Tregs and surprisingly Th17 cells." (PMID 38247848, 2024). "The primary objective of this study is to induce the generation of Tregs from CD4+ T cells by using Aza in vitro, followed by the intravenous infusion of induced Tregs (iTregs) to treat atherosclerosis, in order to elucidate the underlying mechanisms involved." (PMID 39304654, 2024). "The authors contributed this increase in atherosclerosis to a loss of CD4+ T regulatory (Treg) cells, which have been associated with an atheroprotective role." (PMID 37681883, 2023). "Higher circulating levels of CD4+ memory cells have been described to be associated with senescence, atherosclerosis and cardiovascular risks." (PMID 36768814, 2023). "A CD4/CD8 ratio below 0.3 was a diagnostic indicator of atherosclerosis in HIV patients undergoing primary prevention in our sample." (PMID 36627565, 2023). "In accordance, Gaddis and colleagues observed an increased frequency of Nrp-1+CD4+ effector T cells in a model of atherosclerosis that was also associated with an activated phenotype and ablation of Nrp-1 on T cells led to a better disease outcome." (PMID 38019895, 2023). "MiRNA-155 is a typical multifunctional miRNA that has been associated with the occurrence and development of atherosclerosis by regulating the functions of CD4+ T lymphocytes, monocytes/macrophages, endothelial cells (ECs), and vascular smooth muscle cells." (PMID 37628623, 2023).
atherosclerosis (continued). "This genus has been linked with CVD risk factors such as atherosclerosis, AF and hypertension and was more abundant in samples from German patients, were the CD4/CD8 ratio is lower compared to Italian." (PMID 36789351, 2023). "A CD4/CD8 ratio lower than 0.3 was always associated with subclinical atherosclerosis (95% confidence interval (CI): 83.9–100%)." (PMID 36627565, 2023). "Adoptive transfer of ApoB100-pulsed tolerogenic DCs prevented atherosclerosis development in hypercholesterolemic mice by diminishing pathogenic T cell responses to ApoB100 and promoting antigen-specific CD4+Foxp3+ Treg responses." (PMID 34945203, 2021). "In HIV-positive patients, low CD4 cell levels and high VL are associated with an increased risk of subclinical atherosclerosis despite having a low SCORE index." (PMID 34531450, 2021). "In HIV-positive patients, low CD4 cell levels and high VL were associated with risk of developing subclinical atherosclerosis." (PMID 34531450, 2021). "T cells emerge as double-edged swords in the associations between vascular outcomes and CKD, with Tang depletion being associated with poor vascular functionality and subclinical atherosclerosis, whereas CD4+CD28null were related to calcification." (PMID 34113627, 2021). "Recent studies identified Apolipoprotein B (ApoB)—the core lipoprotein of LDL, very-LDL, and chylomicron—as an atherosclerosis-associated antigen that is recognized by CD4+ T cells in the context of proinflammatory cytokines and strong co-stimulation." (PMID 33572939, 2021). "It is important to note that CD4+ T-cells in patients with a high ApoB:ApoA1 ratio showed increased response to oxidative stress signalling, a process that has been implicated in atherosclerosis through oxidization of LDL and altered inflammatory processes." (PMID 33640328, 2021). "Although the data on the role of ABCA1 or cholesterol efflux in lymphocytes are scarce, the impairment of cholesterol efflux has been shown to stimulate the proliferation of CD4+ T lymphocytes, which are implicated in the development of atherosclerosis." (PMID 33658980, 2020). "Increased CD4+ T cell function is associated with worsening of experimental atherosclerosis, which we observed in the male COL6A1-immunized mice." (PMID 32373127, 2020). "Our data were consistent with the observation of the deficiency of Tregs in the experimental atherosclerosis model and suggest decreased CD4+CD25+ Treg participation in plaque destabilization." (PMID 33614738, 2020). "We concluded that B cell FcγRIIb–driven reduction in atherosclerosis was associated with reductions in systemic CD4+ T cell responses and IgG2c class-switched antibody responses." (PMID 31092015, 2019). "Despite CD4 T cells being able to respond to systemic stimulation, collectively congenital B cell deficiency reduced atherosclerosis by reduced B and T cell effector functions." (PMID 31998318, 2019). "In summary, we have shown that congenital global B cell deficiency in μMT−/−ApoE−/− mice decreases atherosclerosis by reducing accumulation of macrophages and CD4 T cells." (PMID 31998318, 2019). "CD4 T cells reactive with β2GPI have also been associated with atherosclerosis and found within atherosclerotic plaques." (PMID 30619248, 2018). "Th1 CD4+ T cells are involved in immunity against pathogens, but have also been implicated in auto-immune and inflammatory diseases such as atherosclerosis." (PMID 30687720, 2018).
atherosclerosis (continued). "miRNA-155 is a typical multifunctional miRNA, which has been associated with the occurrence and development of atherosclerosis by regulating the functions of CD4+ T lymphocytes, monocytes/macrophages, endothelial cells, and vascular smooth muscle." (PMID 30046360, 2018). "A recent study suggested that DJ-1 deficient CD4+ T cells are also able to differentiate into more Th1 and Th17 phenotypes in an atherosclerosis model." (PMID 26634899, 2015). "In the MESA study, which included otherwise healthy individuals, higher circulating CD4+ to CD4+ naïve cells ratio were found to be associated with subclinical atherosclerosis as estimated by carotid ultrasonography." (PMID 25016368, 2014). "Other studies have shown that low CD4 count (<350 cell/mL) is associated with higher rates of CVD or subclinical atherosclerosis." (PMID 24163202, 2013). "At present, there are no studies performed which have assessed the efficacy of interventions aimed at reducing the pathogenic role of proinflammatory CD4+CD28null T cells in atherosclerosis." (PMID 24288592, 2013). "CD4+CD28null T cells have not only been implicated in atherosclerotic plaque rupture but also in early stages of atherosclerosis such as arterial media thickening." (PMID 24288592, 2013). "Recently, it has been reported that genetic deletion of CXCL10 in atherosclerosis susceptible mice also resulted in smaller lesions, which contained fewer CD4+ T cells." (PMID 22164344, 2011). "Our data are the first to show a direct relationship between inhaled pathogenic fibers and the exacerbation of atherosclerosis via a CD4+ T cell–dependent process." (PMID 18795166, 2008). "Additionally, the densities of CD20+ B- and CD4+ T-lymphocytes were associated with atherosclerosis- and inflammation-related changes, such as the accumulation of apolipoprotein B-100 and serum amyloid A, and densities of CD68+ and CD163+ macrophages." (PMID 40498464, 2025). "Future studies, beyond the scope of this work, will likely reveal more in-depth information about the dynamic correlation between CVD-related clinical parameters and enrichment of APOB+ motifs in atherosclerosis-related pathogenic CD4+T cells such as exTregs and effector/memory subsets." (PMID 38571941, 2024). "However, despite markedly impaired peripheral pro-inflammatory Th1 cells and atheromatous CD4+ T cells, the unexpected net effect of hematopoietic PI3Kδ deficiency was aggravated vascular inflammation and atherosclerosis." (PMID 39378110, 2024). "Cytotoxic CD4+ T cells express markers which have been implicated in atherosclerosis in PLWH, including CD57 (a marker of senescence), CX3CR1 (a chemokine receptor that homes cells to inflamed endothelium), and GPR56 (an adhesion g-coupled protein receptor that is expressed on exhausted T cells)." (PMID 39000373, 2024). "CMV-specific CD4+ T cells expressing CX3CR1 are linked to atherosclerosis, and treatments targeting CMV may impact CVD outcomes." (PMID 39000373, 2024). "By contrast, antigen presentation by DCs to CD4+ T cells in the arterial wall causes local T cell activation and production of proinflammatory cytokines, contributing to atherosclerosis, and this event has been recently demonstrated to involved also the direct priming of naïve T cells in the aorta." (PMID 35966516, 2022). "In contrast to B2 cells, however, these cells can diminish inflammation in atherosclerosis by antibody-secretion blocking the uptake of oxLDL and declining the number of associated CD4+ T cells in case of B1 cells and excretion of anti-inflammatory cytokines like IL-10, IL-35 and TGFß in B regs." (PMID 35845058, 2022). "Each subset associated distinctly with adverse vascular outcomes in univariate and multivariate analyses: while Tang depletion was linked to poor vascular function and subclinical atherosclerosis, increases in CD4+CD28null were associated with overt vascular thickening and calcification." (PMID 34113627, 2021).